MANF (mesencephalic astrocyte derived neurotrophic factor)
Diseases named in the same sentence as MANF in open-access papers (continued):
Sharing a sentence is not in itself a finding about the gene and the disease.
diabetes (continued). "Ablation of MANF in mouse embryos, both overall and in the pancreas, leads to early onset and severe diabetes mellitus." (PMID 36936164, 2023). "MANF is an emerging therapeutic target for metabolic diseases, including diabetes 35, obesity 19, fatty liver 20, alcohol-related diseases, and cardiovascular diseases." (PMID 37928262, 2023). "There are several reports, showing alterations in levels of circulating MANF/CDNF in patients with diabetes, autoimmune diseases (rheumatoid arthritis and systemic lupus erythematosus), PD and stroke." (PMID 34575854, 2021). "MANF has shown promising protective effects in neurodegenerative diseases, diabetes, and ischemic diseases of the heart and brain, and it can even modulate inflammatory factor expression to suppress chronic inflammatory diseases." (PMID 34220710, 2021). "Since conventional MANF KO mice develop diabetes by the age of seven weeks, we followed the blood glucose levels to rule out the possible development of hyperglycemia." (PMID 32005751, 2020). "Our results indicate that molecular pathways regulated by MANF are promising therapeutic targets for regenerative therapy of ER stress-related disorders, including diabetes, retinal degeneration, neurodegeneration, and Wolfram syndrome." (PMID 32366942, 2020). "Our results indicate that molecular pathways regulated by MANF are promising drug targets for ER stress-related disorders, including β cell death in diabetes and Wolfram syndrome." (PMID 32366942, 2020). "Since increased serum MANF levels were also observed in PD patients, it is possible that the molecular mechanisms regulating MANF concentrations are similar both in diabetes and in PD." (PMID 31555085, 2019). "We have found that MANF deletion from the pancreas and β-cells leads to postnatal depletion of β-cells and diabetes." (PMID 31781038, 2019). "However, it remains to be determined whether the circulating levels of calcitonin, T4 and T3 and parathyroid hormone are reduced in MANF-deficient mice, which could, in addition to diabetes contribute to the retarded growth and reduced life-span in Manf−/− mice." (PMID 31781038, 2019). "Genetic ablation of the MANF gene in mouse results in progressive postnatal reduction of β-cell mass and severe diabetes, indicating that MANF is required for pancreatic β-cell proliferation and survival." (PMID 29687079, 2018). "The emerging protective and regenerative effects for MANF in mouse and human pancreatic beta cells and diabetes are discussed in this review." (PMID 30386256, 2018). "In support of this idea, a recent study identified MANF as a candidate disease gene in a patient with type 2 diabetes mellitus and obesity." (PMID 28924165, 2017). "MANF is upregulated in response to ER stress-inducing stimuli, and there is chronic upregulation of unfolded protein response markers in the pancreata of MANF knock-out mice, which subsequently develop diabetes." (PMID 28275710, 2017). "Development of MANF-based therapies for diabetes requires detailed characterization of MANF expression and activity." (PMID 27356471, 2016). "Reduced expression of MANF could lead to metabolic dysfunction and apoptosis, potentially contributing to diabetes in the F1." (PMID 40041941, 2025). "However, the expression of MANF is inconsistent in human disease, and studies have shown that circulating serum MANF levels are significantly elevated in patients with primary diabetes and early diabetes with abnormal glucose tolerance." (PMID 34220710, 2021). "MANF signaling is an emerging therapeutic target in neurodegenerative diseases, diabetes mellitus, stroke, retinal damage, and Wolfram syndrome, a genetic disorder characterized by diabetes and retinal and neuronal degeneration." (PMID 33299977, 2020). "In addition, data on the circulating levels of MANF in newly diagnosed diabetes patients support roles for MANF in the regulation of systemic metabolic homeostasis." (PMID 31781038, 2019).
diabetes (continued). "As chronic ER stress precedes the reduced pancreatic β-cells proliferation and increased β-cells death leading to diabetes in Manf−/− mice, we investigated whether ablation of MANF from the pituitary leads to ER stress and chronic UPR activation." (PMID 31781038, 2019). "Thus MANF alone or in combination with other drugs is a potential agent for development into a regenerative drug for beta cells in diabetes." (PMID 30386256, 2018). "Future studies will reveal whether MANF protein-based systemic delivery can normalize blood glucose levels in rodent models of diabetes." (PMID 30386256, 2018). "Furthermore, increased MANF levels has been detected in the sera of young children with newly diagnosed Type 1 (T1D) diabetes and Type 2 (T2D) diabetic patients." (PMID 30386256, 2018). "Recently, studies conducted at the University of Helsinki demonstrated that the concentration of MANF is increased in the serum in children with type 1 diabetes, which indicated that MANF may be used as a potential therapeutic protein for diabetes." (PMID 28367115, 2017). "As a potential therapeutic protein for diabetes MANF needs further attention and investigation." (PMID 27356471, 2016). "Patients lacking functional MANF also exhibit diabetes and hearing loss." (PMID 41339935, 2025). "Notably, mice with the konckout of MANF developed diabetes due to increasing apoptotic cell death and reduced proliferation of pancreatic β cells, while recombinant MANF could promote proliferation and prevent cell death." (PMID 36589805, 2022). "Finally, MANF is a protective factor for diabetes, and PHB knockout mice develop the disease." (PMID 35740256, 2022). "Collectively, our results provide a rationale for identifying signaling molecules regulated by MANF, including its receptor, so that we may develop novel regenerative therapy for ER stress-related disorders, including diabetes, retinal degeneration, and Wolfram syndrome." (PMID 32366942, 2020). "Thus, upregulation of UPR genes Grp78 and sXbp1 was shared between conventional Manf-/- mice and conditional Manffl/fl::NestinCre/+ mice, confirming that this is a phenotype caused by MANF deficiency and not diabetes." (PMID 32005751, 2020). "Thus MANF could be a potential therapeutic factor to alleviate ER stress, rescue beta cells and induce beta cell regeneration in diabetes." (PMID 30386256, 2018). "Importantly, in vivo overexpression of MANF in the pancreas of T1D mice led to increased beta cell proliferation and decreased beta cell death, suggesting that MANF could be a new therapeutic candidate for beta cell protection and regeneration in diabetes." (PMID 30386256, 2018). "Mesencephalic astrocyte-derived neurotrophic factor (MANF) was recently shown to be essential for the survival and proliferation of pancreatic β-cells in mice, where deletion of MANF resulted in diabetes." (PMID 27356471, 2016). "Mesencephalic astrocyte-derived neurotrophic factor (MANF) is an endoplasmic reticulum (ER)-resident secretory protein that has the potential as a therapeutic agent for various diseases related to inflammation and ER stress, such as Type 1 diabetes mellitus." (PMID 39666939, 2024). "As experimentally-induced hyperglycemia and high-fat diet induced diabetes have been shown to increase ER stress and UPR activation in rodent brains, we studied the effect of MANF removal devoid of the hyperglycaemic effect in the brain tissue of Manffl/fl::NestinCre/+ mice." (PMID 32005751, 2020). "The role of KDELR in diabetes has not yet been elucidated; its association with the disease is based on receptor overexpression, its contribution to UPR, and its interaction with PHB and MANF." (PMID 35740256, 2022). "However, it can be speculated that prolonged mild downregulation of MANF/CDNF may contribute to impairment of ER stress response, making cells more vulnerable for various insults and implicating in development and progression of various diseases, such as neurodegeneration or diabetes." (PMID 34575854, 2021).
diabetes (continued). "However, in contrast to diabetes in vivo, C2-ceramide did not increase GRP94 or MANF in GECs, suggesting that the effect of C2-ceramide on autophagy was independent of the UPR." (PMID 38778209, 2024).
Stroke (28 papers, 2014 to 2025). Sudden impairment of blood flow to a part of the brain due to occlusion or rupture of an artery to the brain. "We demonstrate that after stroke, activated microglia/macrophages prominently express MANF in both species and that stroke causes a clear transition of MANF protein expression pattern towards microglia/macrophages." (PMID 38229173, 2024). "Serum MANF levels were analyzed using multivariate analysis with respect to its association with stroke severity and prognosis." (PMID 37268902, 2023). "Using multivariate analysis, NIHSS scores (OR, 1.286; 95% CI, 1.065–1.552; P = 0.009), hematoma volumes (OR, 1.136; 95% CI, 1.068–1.209; P = 0.014) and serum MANF levels > 62.0 ng/ml (OR, 3.848; 95% CI, 1.193–12.417; P = 0.024) were independently associated with a poor prognosis after stroke." (PMID 37268902, 2023). "Decreased MANF expression could predispose for many age-related diseases and worsen the outcome of stroke." (PMID 35783104, 2022). "The most notable effect of MANF was upregulation of transcripts related to immune response, especially toward virus, that could be detected despite the massive inflammation caused by the stroke itself." (PMID 35783104, 2022). "Many studies had shown that MANF plays a protective role in neuronal regeneration, maturation, and differentiation after stroke." (PMID 40919080, 2025). "In intact brain, MANF is predominantly expressed in neurons, while after stroke, MANF expression is downregulated in neurons and upregulated in microglia and astrocytes." (PMID 40919080, 2025). "In our in vivo study, the overall expression of MANF in the peri-infarct zone increased after stroke." (PMID 40919080, 2025). "After stroke, endoplasmic reticulum stress occurs in neurons, astrocytes, and microglia, and MANF expression was found to be upregulated in all of these cells." (PMID 40919080, 2025). "In stroke models, MANF has been shown to protect neural stem cells from hypoxic and glycolytic injury." (PMID 40919080, 2025). "MANF inhibited inflammatory responses and improved blood-brain barrier integrity after stroke in aged mice via the TLR4/MyD88/NF-κB pathway." (PMID 40919080, 2025). "We demonstrate that there is a drastic change in MANF protein expression pattern after stroke in microglia/macrophages." (PMID 38229173, 2024). "Consistently, RNF2 levels in the nucleus were increased in the brain tissue from stroke patients and I/R rats and co‐existed with MANF under ischemic injury." (PMID 39614674, 2024). "This is the first study to show that after stroke MANF protein expression is triggered in microglia/macrophages in the human brain parenchyma." (PMID 38229173, 2024). "To evaluate the potential of MANF as biomarker for stroke, we analyzed MANF levels from mouse serum post-stroke." (PMID 38229173, 2024). "MANF is evidently expressed in phagocytic microglia/macrophages especially around 2 weeks in patients and 1–2 weeks post-stroke in experimental animals." (PMID 38229173, 2024). "We show for the first time how MANF protein expression evolves temporally in the post-stroke human brain and similarly in the rat brain." (PMID 38229173, 2024). "In ischemic conditions, both neurons and astrocytes exhibit elevated MANF expression, which can reverse behavioral deficits induced by stroke, suggesting its critical role in neuroprotection." (PMID 38377025, 2024). "As an attempt to develop a non-invasive method for administering MANF, we show for the first time that intranasally delivered rhMANF reduced infarction size and promoted post-stroke recovery in rats." (PMID 38229173, 2024). "In the non-stroke control brain MANF immunoreactivity was neuronal, as we have seen and reported before." (PMID 38229173, 2024). "Intense MANF immunoreactivity took place in phagocytic microglia/macrophages in the ischemic territory, peaking at two weeks post-stroke in human and one-week post-stroke in rat ischemic cortex." (PMID 38229173, 2024).
Stroke (continued). "To identify which cells express MANF protein after stroke, we used double immunofluorescence staining on sections from the post-stroke rat brain." (PMID 38229173, 2024). "It is also possible that MANF immunoreactivity in microglia/macrophages after stroke is originating from circulating MANF, and in this case these cells would take it up and therefore become MANF-positive for immunoreactivity." (PMID 38229173, 2024). "We showed this with human stroke patients' postmortem brains, rat brains and mouse MANF knockout brains where MANF was deleted from the neuronal lineage of cells (neurons, astrocytes, oligodendrocyte precursors and oligodendrocytes)." (PMID 38229173, 2024). "The most important finding of this study is that there is drastic change of MANF protein expression towards microglia/macrophages after stroke." (PMID 38229173, 2024). "The protein expression of neuronal MANF was found elevated 2–48 h post‐stroke after transient MCAO in the peri‐infarct region." (PMID 39614674, 2024). "The pro-survival effect of Mesencephalic astrocyte-derived neurotrophic factor (Manf) has been shown in multiple disease states such as diabetes, stroke, and neurodegeneration regulating neurogenesis and inflammation." (PMID 37740008, 2023). "Intriguingly, a recent study has reported that serum MANF levels were substantially increased in rats with acute ischemic stroke or patients, and elevated levels of MANF were highly correlated with stroke severity of patients." (PMID 37268902, 2023). "We have shown that Arg1-positive (arginase 1) and phagocytic CD68-positive cells are increased after viral vector-mediated MANF gene delivery in a rat dMCAo cortical ischemic stroke model, coinciding with elevated brain repair processes after stroke." (PMID 35783104, 2022). "Even a single intracranial MANF recombinant protein injection 7 days post-stroke was able to alleviate neurological deficits a week later." (PMID 35783104, 2022). "As quantification of the data between publications is difficult, we used the number of publications reporting the expression of MANF or XBP1 at each time point as an indication of gene expression after stroke resulting in an “overexpression confidence”." (PMID 35783104, 2022). "MANF represents an emerging regulator of tissue clearance after stroke, and at the cellular level, post-stroke MANF delivery supports many endogenous beneficial cellular repair processes that occur after ischemic stroke." (PMID 35783104, 2022). "Post-stroke MANF administration facilitates neurogenesis, promotes innate immunity responses, and enhances angiogenesis." (PMID 35783104, 2022). "In contrast, MANF enhanced stroke recovery and angiogenesis by stimulating the VEGF pathway, depicting quite opposite outcomes while modulating the same pathway." (PMID 35783104, 2022). "The primary focus of this review is to highlight the importance of the UPR and IRE1/XBP1 pathway in brain injuries and the potential of MANF as a therapeutic agent in stroke." (PMID 35783104, 2022). "The protein expression of neuronal MANF was found elevated 2–48 h post-stroke after transient middle cerebral artery occlusion (MCAo) in rats, and most prominently in the peri-infarct region." (PMID 35783104, 2022). "The mechanisms by which MANF promotes recovery after the acute phase of stroke remain poorly understood." (PMID 35783104, 2022). "Increased number of these innate immune cells was observed in the external capsule and dorsal striatum on post-stroke day 4 after peri-infarct area-targeted MANF gene delivery." (PMID 35783104, 2022). "We will focus on comparing the role of XBP1 and MANF in stroke and the function of MANF as a regulator of inflammation and neurogenesis." (PMID 35783104, 2022). "In the rat transient dMCAo model, intracerebral infusion of the recombinant MANF protein starting 3 days post-stroke increased the migration of neural progenitor cells into the infarct region." (PMID 35783104, 2022).